ENSG00000273908
Gene: Miscellaneous RNA gene on chromosome 11 (32,439,716 to 32,440,009, forward strand). Ensembl gene ENSG00000273908.
Homologues: Orthologues: mouse Gm56384 (93% identical).